GSDMD (gasdermin D)
Diseases named in the same sentence as GSDMD in open-access papers (continued):
Sharing a sentence is not in itself a finding about the gene and the disease.
triple-negative breast carcinoma (4 papers, 2022 to 2024). An invasive breast carcinoma which is negative for expression of estrogen receptor (ER), progesterone receptor (PR), and human epidermal growth factor receptor 2 (HER2). "Nigericin causes triple-negative breast cancer cell death by inducing concurrent caspase-1/GSDMD-mediated pyroptosis and promoting the infiltration and activation of T cells, making it a promising antitumour agent, especially when combined with anti-PD-1 antibody treatment." (PMID 39616223, 2024). "Recently published studies have shown that Cisplatin induces scorch death through activating the MEG3/NLRP3/caspase-1/GSDMD pathway in triple-negative breast cancer." (PMID 35938142, 2022). "MEG3 can act as an agonist of cisplatin in suppressing triple-negative breast cancer (TNBC) growth and metastasis potentials, and facilitate pyroptosis by activating cisplatin-induced NLRP3/caspase-1/gasdermin D (GSDMD) pathway." (PMID 36551518, 2022).
Type II Diabetes (4 papers, 2023 to 2025). "In type II diabetes, mitochondrial ROS accumulation activates the NLRP3 inflammasome, which then triggers the Caspase-1/GSDMD pathway and initiates pyroptosis in muscle cells." (PMID 41334559, 2025).
ulcerative colitis (4 papers, 2019 to 2025). An inflammatory bowel disease involving the mucosal surface of the large intestine and rectum. "For studying how NEK7 affected the pyroptosis in IBD, we first examined the mRNA expression and protein levels of NEK7, as well as key factors in pyroptosis, including Caspase-1, NLRP3, and GSDMD, in control and ulcerative colitis tissues in IBD patients." (PMID 31787755, 2019). "The mRNA expression of NEK7, Caspase-1, NLRP3, and GSDMD showed to be remarkably increased in ulcerative colitis tissue samples than that in control tissues." (PMID 31787755, 2019).
acute respiratory distress syndrome (3 papers, 2024 to 2025). Progressive and life-threatening pulmonary distress in the absence of an underlying pulmonary condition, usually following major trauma or surgery. "Our prior investigations have elucidated the pivotal role of neutrophil GSDMD-mediated NETosis in acute respiratory distress syndrome (ARDS)." (PMID 39972252, 2025). "GSDMD cleavage was previously shown to be upstream to NET release in neutrophils during acute respiratory distress syndrome, where extrinsic NETs could significantly reverse the protection of GSDMD inhibition against mouse lung injury." (PMID 39253076, 2024).
adrenocortical carcinoma (3 papers, 2023 to 2024). "For example, as an critical link in the development of pyroptosis, high expression of GSDMD in some tumors can improve the survival time of patients, while high expression of GSDMD often leads to poor prognosis in adrenocortical carcinoma, chromophobe renal cell carcinoma and other tumors." (PMID 37313458, 2023).
amyotrophic lateral sclerosis (3 papers, 2023 to 2025). Amyotrophic lateral sclerosis (ALS) is a neurodegenerative disease characterized by progressive muscular paralysis reflecting degeneration of motor neurons in the primary motor cortex, corticospinal tracts, brainstem and spinal cord. "The elevated formation of inflammasomes, expression of IL-1β and IL-18, and excessive cleavage of GSDMD have been reported in amyotrophic lateral sclerosis (ALS) and multiple sclerosis (MS) cases, indicating a crucial role for pyroptosis in the neuroinflammation and development of ALS." (PMID 39337436, 2024). "Similarly, activation of the NLRP3 inflammasome and subsequent GSDMD cleavage have been observed in the microglia of amyotrophic lateral sclerosis (ALS) patients and in Parkinson’s disease (PD) mouse models." (PMID 39994107, 2025). "In motor neuron diseases, studies have found that the expression level of the pyroptosis marker GSDMD is increased in spinal cord samples of amyotrophic lateral sclerosis (ALS) patients, indicating that microglial pyroptosis may play an important role in the pathogenesis of ALS." (PMID 38020781, 2023).
breast invasive carcinoma (3 papers, 2022 to 2024). "We show that GSDMD mRNA expression is upregulated in several types of human cancer and that this is associated with profound changes in the transcriptional profile of immune cell-associated genes in primary breast invasive carcinoma (BRCA) and liver hepatocellular carcinoma (LIHC)." (PMID 39224600, 2024). "The potential impact of intratumoral GSDMD expression on survival outcomes and immune cell-related genes was examined in, primary breast invasive carcinoma (BRCA) and liver hepatocellular carcinoma (LIHC)." (PMID 39224600, 2024). "Higher GSDMD expression correlated with increased survival in primary breast invasive carcinoma (BRCA), but not in liver hepatocellular carcinoma (LIHC)." (PMID 39224600, 2024).
bronchopulmonary dysplasia (3 papers, 2025). Bronchopulmonary dysplasia is a chronic respiratory disease that results from complications related to lung injury during the treatment of infant acute respiratory distress syndrome in low-birth-weight premature infants or from abnormal lung development in older infants. "VX-765 inhibited NLRP3/Caspase-1/GSDMD-mediated macrophage pyroptosis in the mice lung tissue of bronchopulmonary dysplasia (BPD)." (PMID 40486518, 2025). "METTL3 aggravates pulmonary inflammation in bronchopulmonary dysplasia by mediating the m6A modification of ATG8, suppressing its expression, disrupting the GSDMD interaction, inhibiting autophagy, and inducing pyroptosis." (PMID 41105618, 2025). "Bronchopulmonary dysplasia (BPD), a frequent complication in preterm infants receiving supplemental oxygen, is characterized by hyper-activation of macrophage inflammasomes, exuberant release of pro-inflammatory cytokines such as interleukin-1β (IL-1β), and Gasdermin D (GSDMD)-driven pyroptosis." (PMID 41345109, 2025).
chronic kidney disease (3 papers, 2024 to 2025). Impairment of the renal function secondary to chronic kidney damage persisting for three or more months. "Gasdermin D (GSDMD)-mediated pyroptosis amplifies the inflammatory and fibrogenic cascade, yet its role in chronic kidney disease (CKD) remains elusive." (PMID 41387110, 2025). "In the context of AKI and chronic kidney disease (CKD), GSDMD expression dynamics and its implications vary." (PMID 38740765, 2024).
Crohn disease (3 papers, 2021 to 2023). A gastrointestinal disorder characterized by chronic inflammation involving all layers of the intestinal wall, noncaseating granulomas affecting the intestinal wall and regional lymph nodes, and transmural fibrosis. "Pyroptosis plays a crucial role in driving the inflammatory response, but it remains unclear whether GSDMD-mediated pyroptosis contributes to the pathogenesis of Crohn’s disease (CD)." (PMID 37131223, 2023).
demyelination (3 papers, 2022 to 2024). "A more recent study showed increased expression of GSDMD in both oligodendrocytes and microglia in the brain tissues of patients with progressive multiple sclerosis (P-MS), and GSDMD knockout in a cuprizone (CPZ)-induced demyelination mouse model reduced demyelination and neuronal axon damage." (PMID 39710713, 2024). "Similarly, we found caspase-1, GSDMD, NLRP3 and IL-1β mainly localize in microglia, suggesting microglia as the dominating cell type that undergo pyroptosis in our LPC-induced demyelination model." (PMID 36803990, 2023).
dry eye (3 papers, 2021 to 2023). "The dry eye signs, such as tear loss or inflammatory response, can be aggravated by NLRP12/NLRC4 inflammasome activation mediated GSDMD cleavage together with IL-33 and IL-1β." (PMID 36614174, 2023). "A recent study examined the increased expression of the pyroptosis executor GSDMD N-terminal domain in tears from dry eye patients and demonstrated direct evidence of the involvement of pyroptosis in dry eye patients." (PMID 34925047, 2021). "Desiccating stress–induced TLR4 activation promotes NLRP12, and NLRC4 inflammasome–mediated GSDMD-dependent pyroptosis is responsible for processing bioactive IL-33, which exacerbates inflammation in dry eye via caspase-8 signaling." (PMID 34925047, 2021). "GSDMD-driven pyroptosis in desiccating stress–induced dry eye mice has been demonstrated." (PMID 34925047, 2021). "NLRP12/NLRC4 knockdown, GSDMD knockout, or the neutralization of mature IL-33 can obviously attenuate the damage to corneal epithelial cells, indicating that these molecules could be key targets for dry eye treatment in the future." (PMID 37250902, 2023).
fungal infection (3 papers, 2022 to 2025). "Moreover, western blot analysis revealed dramatically decreased levels of pyroptosis-associated proteins ASC, cleaved CASP1, GSDMD, cleaved GSDMD, cleaved IL-1β and cleaved IL-18 in the Ad-NLRP3-shRNA group compared with the Ad-GFP-shRNA group during fungal infection." (PMID 35463001, 2022). "During fungal infection, the activation of the NLRP3-ASC-CASP1 inflammasome leads to cleavage of pro-CASP1, which then processes the proinflammatory cytokines IL-1β and IL-18 to their bioactive forms and cleaves GSDMD to trigger pyroptosis." (PMID 35463001, 2022). "Although the role of GSDMD in fungal infectious diseases has not been defined exactly, as the downstream of AIM2 and NLRP3 inflammasome, GSDMD is believed to play critical role in these diseases." (PMID 35774778, 2022).
hyperuricemia (3 papers, 2021 to 2025). An abnormally high level of uric acid. "Tissue immunofluorescence results indicated that the expression of NLRP3, caspase‐1 and GSDMD‐FL was distributed throughout the glomeruli of the hyperuricaemia group; the glomerular fluorescence intensity in the hyperuricaemia group was significantly higher than that in the control group." (PMID 34296520, 2021).
injury (3 papers, 2022 to 2023). Damage inflicted on the body as the direct or indirect result of an external force, with or without disruption of structural continuity. "In this study, we focused our investigations on the effects of GSDMD-KO in a neonatal mouse model of hyperoxia-induced brain injury." (PMID 37398125, 2023). "In this study, we focused our investigations on the effects of global GSDMD-KO in a neonatal mouse model of hyperoxia-induced brain injury." (PMID 37679766, 2023). "Previous studies from our lab have demonstrated a critical role for GSDMD activation in hyperoxia-induced mouse model of BPD and brain injury." (PMID 37398125, 2023). "Previous studies from our lab have demonstrated a critical role for GSDMD activation in hyperoxia-induced mouse models of BPD and brain injury." (PMID 37679766, 2023).
Insulin resistance (3 papers, 2022 to 2026). Increased resistance towards insulin, that is, diminished effectiveness of insulin in reducing blood glucose levels. "As-induced NRLP3 inflammasome activation along with inhibition of gasdermin D ubiquitination resulted in promotion of gasdermin D-mediated pyroptosis and subsequent hepatic insulin resistance." (PMID 37624175, 2023). "As adipocyte hypertrophy is known as a dominant mechanism of fat cell expansion and enhanced susceptibility to insulin resistance in humans, our results imply a noncanonical function of GSDMD in maintaining adipose tissue plasticity through the regulation of PPARγ." (PMID 36065376, 2022).
malaria (3 papers, 2017 to 2022). Malaria is a serious and sometimes fatal disease caused by a parasite that commonly infects a certain type of mosquito which feeds on humans. "Interestingly, one of these regions, 8q24.3 contains: the c-Myc gene; GSDMD, encoding inflammasome substrate gasdermin D; and a novel, uncharacterised locus of resistance to severe malaria." (PMID 28923166, 2017). "Knockout of caspase-8/1/11 or caspase-8/GSDMD resulted in disruption of TNF-α and IL-1β production, uncovering a supplementary and indispensable role for caspase-8 and GSDMD in malaria pathogenesis." (PMID 35795683, 2022).
migraine (3 papers, 2022 to 2025). "Several other studies have also investigated and revealed the role of GSDMD in the pathogenesis of neurological disorders, including acute ischemic stroke and migraine, indicating its potential as a therapeutic target in these conditons." (PMID 40418140, 2025). "The similar cellular localization of CC1 and GSDMD provides evidence for the occurrence of inflammasome-mediating pyroptosis in cortical and hippocampal neurons and microglia in an IS-induced migraine mouse model." (PMID 35780081, 2022).
myocarditis (3 papers, 2022 to 2025). Myocarditis is a condition that is characterized by inflammation of the heart muscle (myocardium). "In terms of diagnosis, endomyocardial biopsy showing active caspase-1 or GSDMD pores could help confirm myocarditis and distinguish it from ischaemic injury." (PMID 40832143, 2025). "Recent evidence implicates pyroptosis in ICI myocarditis: a 2024 study found that gasdermin E (GSDME) –mediated pyroptosis (rather than GSDMD) is extensively activated in ICI-related myocarditis, both in a mouse model and in patient heart samples." (PMID 40832143, 2025). "We found in this study that the levels of GSDMD protein were markedly decreased in VMC with IL-37 treatment compared with the VMC group (P < 0.001), which implied that IL-37 inhibits pyroptosis in CVB3-induced myocarditis." (PMID 36418383, 2022).
oral cancer (3 papers, 2021 to 2024). "Besides, AIM2 and GSDMD showed higher expression in oral cancer cells than HOK cells, especially in HSC-4 cells." (PMID 34384029, 2021). "Furthermore, okanin reduced the expression of GSDMD and GSDME in oral cancer cells." (PMID 39335166, 2024).
oral squamous cell carcinoma (3 papers, 2021 to 2025). "In this work, it is found that low‐dose cisplatin promoted oral squamous cell carcinoma migration, invasion and lymph node metastasis, and gasdermin D (GSDMD) is identified as a potential regulator." (PMID 40178046, 2025).
osteoporosis (3 papers, 2024 to 2025). A condition of reduced bone mass, with decreased cortical thickness and a decrease in the number and size of the trabeculae of cancellous bone (but normal chemical composition), resulting in increased fracture incidence. "The deletion of GSDMD results in the development of severe osteoporosis associated with aging and characterized by significant trabecular bone loss." (PMID 40354374, 2025). "However, the correlation between osteoporosis and lysosomal function remains unclear Gasdermin D (GSDMD) facilitated pyroptosis modulaters immunogenic cell death and inflammation." (PMID 40354374, 2025).
pulmonary hypertension (3 papers, 2022 to 2025). Increased pressure within the pulmonary circulation due to lung or heart disorder. "A number of studies have demonstrated the association of NLRP3 inflammasome and GSDMD in pulmonary hypertension." (PMID 40948742, 2025). "Understanding the interactive and feedback mechanism between NLRP3 inflammasome, S100A8/A9, and GSDMD is necessary to explore their role in pulmonary hypertension." (PMID 40948742, 2025). "Both NLRP3 and GSDMD have been found playing a role in pulmonary hypertension by activating the proinflammatory cytokines and releasing cytosolic contents into the extracellular space." (PMID 40948742, 2025). "In particular, GSDMD mediated pyroptosis plays major role in endothelial dysfunction, which leading to pulmonary hypertension." (PMID 40948742, 2025). "However, the contribution of NLRP3 inflammasome, S100A8/A9, and GSDMD as a team to pulmonary hypertension is unclear." (PMID 40948742, 2025).
renal carcinoma (3 papers, 2022 to 2024). A carcinoma arising from the epithelium of the renal parenchyma or the renal pelvis. "Importantly, we found that the expressions of GSDMB, GSDMC, and GSDMD were higher in kidney carcinomas, and specifically kidney renal clear cell carcinoma (KIRC); which adversely impacted the patient outcome." (PMID 36003332, 2022). "Interestingly, the combination of SGI‐1027 and everolimus induced cleavage of PARP and GSDME, rather than GSDMD, indicating that their combination induced apoptosis and GSDME‐dependent pyroptosis in renal cancer cells." (PMID 39119834, 2024).
schwannoma (3 papers, 2021). A benign, usually encapsulated slow growing tumor composed of Schwann cells. "A novel strategy combining adeno-associated virus delivery and the GSDMD N-terminus is suggested to restrict the growth of schwannomas." (PMID 34522213, 2021). "Likewise, overexpression of GSDMD-NT caused death of human schwannoma cells in vitro." (PMID 33634141, 2021). "Intratumoral injection of adeno-associated serotype 1 virus vectors containing GSDMD-NT transgene (AAV1-rP0-GSDMDNterm) promoted pyroptosis and repressed tumor growth in both mouse schwannoma allograft tumors and human schwannoma xenografts." (PMID 33634141, 2021). "This gene not only shows no neurotoxicity to adjacent tissues after an intratumor injection but also leads to growth suppression in the schwannoma cell lines NF2 and HEI-193 through GSDMD-mediated pyroptosis." (PMID 34522213, 2021).
silicosis (3 papers, 2022 to 2025). Silicosis is a respiratory disease caused by breathing in (inhaling) silica dust. "For example, in silicosis, caspase-1-mediated cleavage of gasdermin D (GSDMD) and caspase-3/8-mediated cleavage of gasdermin E (GSDME) drive pyroptotic cell death." (PMID 40384344, 2025). "GSDMD-mediated pyroptosis was observed in the lung tissues of both silicosis patients and mice." (PMID 39795884, 2024). "The results showed that the cleavage of GSDMD and GSDME were significantly enhanced in silicosis patients." (PMID 36459518, 2022).
spinal cord injury (3 papers, 2023 to 2025). Penetrating and non-penetrating injuries to the spinal cord resulting from traumatic external forces (e.g., WOUNDS, GUNSHOT; WHIPLASH INJURIES; etc.). "GSDMD-mediated pyroptosis can further regulate spinal cord injuries (SCI)." (PMID 36967609, 2023).
Splenomegaly (3 papers, 2023 to 2024). Abnormal increased size of the spleen. "In a mouse FMF model, GSDMD−/− mice exhibited complete protection from systemic inflammatory cytokines production, weight loss, splenomegaly, and liver damage, and pharmacological inhibition of GSDMD achieved similar protective effects." (PMID 38584157, 2024). "GSDMD knockout rescued the severe disease-related facial damage and splenomegaly after pristane treatment." (PMID 36797275, 2023).
status epilepticus (3 papers, 2021 to 2026). Status epilepticus is defined as a continuous seizure lasting more than 30 min, or two or more seizures without full recovery of consciousness between any of them. "We subsequently established a kainic acid-induced status epilepticus (SE) model in mice and validated the mRNA and protein expression of GSDMD and GSDME, the key molecules of pyroptosis, by quantitative reverse transcription PCR (qRT-PCR) and western blotting (WB)." (PMID 35095728, 2021).
subarachnoid hemorrhage (3 papers, 2020 to 2025). A serious neurological disorder characterized by intracranial hemorrhage into the subarachnoid space. "Similarly, inhibition of GSDMD activity in murine subarachnoid hemorrhage attenuates neuronal and microglial injury, abrogating pro-inflammatory activity post-injury." (PMID 40331993, 2025).
tauopathies (3 papers, 2022 to 2026). "Therefore, cleavage of the GSDMD in the hippocampal-formation neurons might be more related to general brain aging and genetic predisposition to distinct tauopathies than to AD per se." (PMID 35883667, 2022). "While GSDMD inhibition mitigates inflammation, its absence exacerbates synaptic impairment, highlighting its complex role in tauopathies." (PMID 41486173, 2026). "Finally, we investigated whether pharmacological modulation of GSDMD through dimethyl fumarate (DMF) treatment could serve as a novel therapeutic strategy for tauopathies." (PMID 41486173, 2026).